GLP1R (glucagon like peptide 1 receptor)
Diseases named in the same sentence as GLP1R in open-access papers (continued):
Sharing a sentence is not in itself a finding about the gene and the disease.
insulinomas (continued). "Although none of these undecapeptides were converted into an imaging agent for insulinomas so far, they might potentially serve as a basis for GLP-1R radioligand with an improved pharmacokinetic profile." (PMID 34432147, 2021). "68Ga-DOTA-exendin-4 PET/CT, using the GLP-1R-targeting peptide exendin-4, is likely to become the diagnostic method of choice for suspected insulinoma negative on conventional imaging." (PMID 34735669, 2021). "Finally, five of these patients had a confirmed insulinoma with normalization of hyperinsulinism after surgery, supporting the clinical value of GLP-1R imaging." (PMID 31951592, 2020). "Indeed, the GLP-1R is also overexpressed in insulin-producing islet cell tumors, that is, insulinomas." (PMID 31951592, 2020). "On the other hand, it should also be noted that the uptake in GLP-1R rich target tissues (e.g. pancreas or insulinoma) of radio-halogenated exendin analogues may similarly be decreased by the lack of a radionuclide trapping mechanism." (PMID 31903131, 2020). "Contrary to benign insulinomas malignant insulinomas more often express SSTR2 than GLP-1R." (PMID 31951592, 2020). "However, the very high and sustained uptake of radiolabeled GLP-1R-targeting Exendin 4 derivatives in kidneys hinders the application of these tracers for detecting insulinomas." (PMID 32854201, 2020). "Research in molecular targeting of GLP-1R expressed on beta cells 43 and involved in various pathological processes, e.g. in insulinomas, gastrinomas, and phaeochromocytomas 23, 32, 33, 41 has been expanding very fast since the development of metabolically stable ligands, e.g. exendin-4." (PMID 31903131, 2020). "Indeed, GLP-1R targeting tracers, such as [68Ga]- or [111In]-labeled exendin, can be applied for non-invasive in vivo insulinoma detection." (PMID 29440684, 2018). "Despite growing evidence for GLP-1R molecular-based imaging, successful localization of insulinomas may require the use of multiple imaging modalities." (PMID 29636947, 2018). "Insulinoma exhibited higher GLP-1R density than normal pancreatic sections as expected." (PMID 28891030, 2017). "The affinity is nanomolar with small inter-species variability except for human insulinoma GLP-1R." (PMID 28891030, 2017). "Especially in patients without pathological findings in routine diagnostic GLP-1R imaging was helpful to localize insulinoma." (PMID 26034506, 2015). "In our view preoperative GLP-1R imaging is important for planning surgical treatment in insulinoma." (PMID 26034506, 2015). "[Lys40(Ahx-DTPA-111In)NH2]-exendin-4, a radiopeptide that selectively binds to GLP-1R expressed on insulinoma and other neuroendocrine tumor cells, was co-administered with oral vatalanib (an inhibitor of vascular endothelial growth factor receptors (VEGFR)) or imatinib (a c-kit/PDGFR inhibitor)." (PMID 24528513, 2014). "High GLP-1R levels were found in only 36% malignant insulinomas." (PMID 23230431, 2012). "This provided the proof of principle for GLP-1R targeting of insulinoma." (PMID 23230431, 2012). "Indeed, 10 years ago, the GLP-1R was found to be expressed in insulin-producing islet cell tumors, i.e., insulinomas." (PMID 23230431, 2012). "The most striking GLP-1R expression was found in insulinoma." (PMID 23230431, 2012). "In particular, virtually all benign insulinomas highly overexpress GLP-1 receptors (GLP-1R)." (PMID 23230431, 2012). "Thus, one can hypothesise that GLP-1R PET/CT will reduce the number of occult insulinomas and can consecutively increase the rate of successful minimally invasive operations of occult insulinomas even further in the future." (PMID 41375058, 2025). "[68Ga]Ga-NOTA-MI-exendin-4 showeda renal uptake thatwas 70% lower than [68Ga]Ga-NOTA-exendin-4 in BALB/c nudemice, while the radiotracer uptake in the INS-1 tumor was preserved,which could potentially increase the sensitivity of GLP-1R PET/CTto detect insulinomas." (PMID 37265006, 2023).
insulinomas (continued). "Interestingly, the GLP-1R density/expression was significantly higher (overexpressed) in insulinomas (high expression in benign insulinomas and lesser expression in malignant/metastasizing insulinoma) and medullary thyroid carcinomas) and other endocrine, embryonal, and brain tumors." (PMID 36358930, 2022). "However, GLP-1R are expressed with a high incidence and at high density in insulinomas." (PMID 34735669, 2021). "Importantly, an extensive evaluation concerning the potential of the GLP-1R for targeted tumor imaging confirmed a nearly 100% incidence of GLP-1R expression on benign insulinomas with an about 5x higher density of GLP-1R on insulinomas compared to normal beta cells." (PMID 31951592, 2020). "This is not surprising considering the fact that normal pancreatic islets express the GLP-1R, and the GLP-1R has been demonstrated to be overexpressed in some panNETs, mainly insulinomas, with contrasting evidence in metastatic lesions." (PMID 40175622, 2025). "Since indolent insulinomas express somatostatin receptors (SSTRs) and glucagon-like peptide-1 receptors (GLP-1Rs), SSTR or even more sensitive GLP-1 receptor imaging can also be used." (PMID 39330031, 2024). "Even before the discovery of exendin-4, its homolog exendin-3 was successfully synthesized by 125I labeling and utilized in two models of insulinoma (NEDH rats and RINm 5F cells), which opened the chapter of GLP-1R imaging for 21 years." (PMID 37780209, 2023). "We used incretin-responsive rat insulinoma-derived INS-1 832/3 cells, in which we first confirmed expression of GLP-1R, GIPR, and GCGR by qPCR." (PMID 33268378, 2021). "The glucagon-like peptide 1 receptor (GLP-1R) is mainly expressed on the pancreatic beta cells and is therefore an interesting target for imaging of occult insulinomas." (PMID 34199977, 2021). "The follow-up of the late accumulation of Mn revealed a specific retention of 55Mn in the native islets and insulinomas as observed from merged elemental images of 55Mn, 64Zn and 44Ca and the accumulation of PET tracer targeting GLP-1R." (PMID 31903128, 2020). "The results indicate that 68Ga-DOTA-exendin-4 PET/CT is indeed able to localized insulinomas in MEN-1 patients with high accuracy, i.e. in the context of MEN-1 insulinomas overexpress GLP-1R as in patients with sporadic insulinomas." (PMID 31951592, 2020). "SPECT/CT imaging is a very promising technique for insulinoma localization, and uses radionuclide-labeled glucagon-like peptide-1 receptor agonist (GLP-1RA) to bind to glucagon-like peptide-1 receptor (GLP-1R) for radionuclide imaging." (PMID 31743337, 2019). "Targeting the GLP-1R using peptide analogs of GLP-1 and exendin-4 have been shown to be useful in imaging benign insulinomas and transplanted islets, but have very limited capacity to image beta cells in the native rodent pancreas." (PMID 27909574, 2016). "In insulinomas, for example, the density of the glucagon-like peptide 1 receptor (GLP-1R) is considerably higher than in normal pancreas (mean density of 8,302 ± 1,073 dpm/mg in benign human insulinomas vs. 1,563 ± 104 dpm/mg in normal endocrine pancreas)." (PMID 22358499, 2012). "As indolent insulinomas tend to express GLP-1Rs, this may be used to the clinician’s advantage, and GLP-1R PET scans have reasonably high sensitivity and specificity (87% and 94%, respectively)." (PMID 40648766, 2025). "Glucagon-Like Peptide-1 Receptor/PET-CT most frequently localised the conventionally non-visible insulinomas (positive in 67/76, 88.2%)." (PMID 41375058, 2025). "In contrast to insulinomas, cross-sectional imaging is usually negative in adult nesidioblastosis; however, a diffuse increase in GLP-1R PET/CT can be detected." (PMID 41375058, 2025). "Insulinomas in particular exhibit receptors such as the growth inhibitory receptor 2 (SSTR2) and the glucagon‐like peptide‐1 receptor (GLP‐1 receptor), with over 90% of these tumors expressing the GLP‐1 receptor." (PMID 39935661, 2025).
insulinomas (continued). "GLP-1R is overexpressed in 93% of the cases, consequently GLP-1 PET/CT improves insulinoma detectability vastly; however, overexpression is only present in 36% of patients with metastases and/or malignant lesions, making the method less informative in the rare but more malevolent malignant cases." (PMID 39497809, 2024). "All three of the insulinomas, in which the insulin staining was considered weak, also lacked the expression of GLP-1R." (PMID 37894845, 2023). "Despite the small number of metastatic insulinomas, our study clearly indicated a significant difference in the GLP-1R expression between metastatic and non-metastatic insulinomas." (PMID 37894845, 2023). "In conclusion, all sporadic, non-metastatic insulinomas in our study expressed GLP-1R, while the lack of GLP-1R was associated with a metastatic disease and impaired survival." (PMID 37894845, 2023). "This cohort included two MEN1-related insulinomas, of which one expressed GLP-1R and the other one did not." (PMID 37894845, 2023). "Of the four insulinomas that lacked the expression of GLP-1R, three were metastatic and one was non-metastatic, but the patient had MEN1 syndrome." (PMID 37894845, 2023). "A false negative insulinoma on histopathology was due to the lack of GLP-1R expression in the lesion." (PMID 37109517, 2023). "None of the GLP-1R-positive insulinomas metastasized during the median follow-up of 11 years (range 0.2–32) after the primary surgery." (PMID 37894845, 2023). "Two of the three patients with metastatic, GLP-1R-negative insulinomas died 1 and 4 years after the primary surgery, while the third patient was alive at the end of the follow-up (over 6 years after the surgery)." (PMID 37894845, 2023). "GLP-1R molecular imaging will become the ideal choice for non-invasive localization and diagnosis of benign insulinoma patients in the future." (PMID 37780209, 2023). "Malignant insulinomas express sstr in density adequate to the imaging and GLP-1R to much lesser or non-existent extent." (PMID 28295000, 2017). "Both modalities did not detect the insulinoma of 1.6 cm in the pancreatic tail, that became visible in GLP-1R imaging." (PMID 26034506, 2015). "Since insulinomas are often somatostatin receptor negative, specific imaging ligands for insulinomas targeting the glucagon-like peptide 1 receptor have been developed." (PMID 25959100, 2015). "Therefore, 83.3% of insulinomas were positive for both the GCGR and GLP-1R." (PMID 40649254, 2025). "Our in vitro analyses further corroborate the observed differences in GLP-1R expression between pNETs and healthy tissue; nevertheless, pNET cell lines used in this study are not insulinoma-derived, and the lack of pNET representative cell lines is a technical difficulty." (PMID 40649254, 2025). "Thus, GLP-1R is a promising biomarker for differentiating between non-metastatic insulinomas and tumours with a more aggressive behaviour." (PMID 37894845, 2023). "Initially, Wild was the first to successfully visualize insulinomas in preclinical studies utilizing Ahx as a linker between DTPA and peptide by c-terminal extension of the Lys side chain coupling of exendin-4 (Lys40NH2 modifies Exendin-4), a landmark for GLP-1R molecular visualization." (PMID 37780209, 2023). "Although the tracers 18F-TTCO-Cys40-Exendin-4 and 64Cu-DO3A-VS-Cys40-Exendin-4 displayed highly specific binding to GLP-1R in the mouse insulinoma model, they did not provide sufficient contrast for PET islet imaging in a mouse model of human islet transplantation." (PMID 30952975, 2019). "In addition to demonstrating in vitro cAMP activity at human and mouse GLP-1R in transfected CHO and in the mouse MIN6 insulinoma cells, MEDI4166 induced glucose-stimulated insulin secretion in INS1 β-cells and displayed a desirable profile in rodent disease models." (PMID 30510163, 2018).
insulinomas (continued). "Selective arterial stimulation and venous sampling correctly indicated the vascular territory, but since this patient had an ectopic insulinoma, the results of the invasive investigation without GLP-1R imaging would have been misleading for the surgical strategy." (PMID 23230431, 2012). "Thus, GLP-1R-positivity is not restricted to insulinoma or insulin IHC-positive pNETs." (PMID 41312422, 2025). "Furthermore, the conclusive confirmation that a lack of GLP-1R expression could be used as a negative prognostic marker in insulinomas would require additional studies investigating a higher number of metastatic insulinomas." (PMID 37894845, 2023). "However, as opposed to benign insulinomas, malignant insulinomas often lack the GLP-1R." (PMID 34199977, 2021). "The GLP-1R-negative, MEN1-related insulinoma did not metastasize during the follow-up of over 20 years." (PMID 37894845, 2023). "GLP-1R PET/CT imaging has proved to be a highly sensitive method for localising small, non-metastatic insulinomas." (PMID 37894845, 2023). "As only two patients had a MEN1-related insulinoma, one expressing and the other one not expressing GLP-1R, we were not able to draw conclusions from the GLP-1R expression of MEN1-related insulinomas in general." (PMID 37894845, 2023). "All sporadic, non-metastatic insulinomas expressed GLP-1R, whereas all three of the metastatic insulinomas lacked the expression of GLP-1R." (PMID 37894845, 2023). "Our cohort included two MEN1-related insulinomas: one of them showed strong expression of GLP-1R, and the other one lacked the expression of GLP-1R." (PMID 37894845, 2023). "The results indicated that patients with the non-insulinoma pancreatic hypoglycemic syndrome (NIPHS) and post-gastric bypass hypoglycemic syndrome (PGBH) could not be distinguished via GLP-1R molecular imaging." (PMID 37780209, 2023). "However it is important to know that many malign insulinomas lack GLP-1R and will not be detectable by GLP-1R targeted imaging." (PMID 26034506, 2015). "Even in cases of negative preoperative imaging, including negative GLP-1R PET/CT, the available literature suggests that minimally invasive exploration with endoscopic ultrasound is feasible and safe if patients display persisting symptoms indicative of an insulinoma." (PMID 41375058, 2025). "Therefore, GLP-1R PET/CT may be a helpful tool in differentiating insulinomas from other PanNETs present in MEN1 patients and guiding successful surgical intervention, albeit it is does not seem to be useful in metastatic insulinomas." (PMID 38893191, 2024).
Parkinson disease (89 papers, 2008 to 2026). A progressive degenerative disorder of the central nervous system characterized by loss of dopamine producing neurons in the substantia nigra and the presence of Lewy bodies in the substantia nigra and locus coeruleus. "Background and aims: Glucagon‐like peptide‐1 receptor (GLP‐1R) agonists, primarily used for treating diabetes, have recently demonstrated neuroprotective properties in a mouse model for Parkinson's disease (PD)." (PMID 40542581, 2025). "Preclinical studies involving GIP and GLP-1R agonists have shown promising results in preclinical models of Parkinson’s disease, indicating their potential as a therapeutic target for both symptomatic relief and disease modification." (PMID 40003982, 2025). "These properties have sparked interest in GLP-1R agonists as potential treatments for neurological disorders, such as Parkinson’s disease (PD) and Alzheimer’s disease (AD)." (PMID 38997662, 2024). "CCK and GLP1 are implicated in neuroprotection and neurite outgrowth within the central nervous system (CNS), with GLP1R agonists offering therapeutic avenues for Alzheimer's and Parkinson's disease." (PMID 38013211, 2024). "The neuroprotective effects of GLP-1R agonists and their exact mechanisms have been studied in Alzheimer’s disease, Parkinson’s disease, vascular brain injury, epilepsy, and other neuropathological diseases." (PMID 37970444, 2023). "This pathway is one of the mechanisms through which GLP-1R agonists are thought to provide neuroprotection in multiple in vitro and animal models of Parkinson’s and Alzheimer’s neurodegeneration." (PMID 37362000, 2023). "GLP-1/GLP-1R also plays a neuroprotective role in cerebral ischemia, craniocerebral trauma, Alzheimer’s disease, Parkinson’s disease, and many other neurodegenerative diseases." (PMID 37970444, 2023). "This evidence raises the potential of GLP-1R agonists for treating both rare and more common neurological diseases with a strong mitochondrial component e.g. PRKN- or PINK1-associated Parkinson’s Disease." (PMID 35970890, 2022). "Yun and co-workers showed that activation of GLP-1R in microglia effectively blocked the conversion of toxic astrocytes in Parkinson's disease." (PMID 35280691, 2022). "GLP-1R agonist exerts a protective effect on Alzheimer's disease and Parkinson's disease 17-19 using its ability to traverse the blood-brain barrier 20,21." (PMID 35280691, 2022). "Glucagon-like peptide-1 receptor (GLP-1R) activation by exendin-4 (EX-4) is effective in preclinical models of Parkinson's disease (PD) and appears to promote neurogenesis even in severely lesioned rats." (PMID 26316987, 2013). "In the central nervous system (CNS), GLP-1R activation initiates a signaling cascade that inhibits the release of proinflammatory cytokines and microglia transformation, both key contributors to Parkinson’s and Alzheimer’s pathogenesis." (PMID 37362000, 2023). "However, NLY01, a GLP1R agonist, exerts a neuroprotective effect in Parkinson’s disease by inhibiting the formation of A1 reactive astrocytes." (PMID 35415238, 2022). "There is growing evidence that GLP-1R activation exerts neuroprotective effects on oxidative stress, neuronal apoptosis, and neuroinflammation in patients with Alzheimer’s disease (AD) or Parkinson’s disease (PD)." (PMID 36615696, 2022). "In addition, a previous study demonstrated that NLY01, a GLP1R agonist, protects dopaminergic neurons from death and improves behavioral recovery in Parkinson’s disease, which is mediated by the block of A1 astrocyte transformation." (PMID 35656116, 2022). "Here we confirm that GLP-1R agonists may offer additional benefits to support the survival and function grafted cells for the treatment of Parkinson’s but that this may be in a L-dopa dependent manner." (PMID 34830228, 2021).